LSP1 (lymphocyte specific protein 1)
Description:
May play a role in mediating neutrophil activation and chemotaxis.
Synonyms: pp52; WP34
Tractability: Antibody: UniProt places it where antibodies can reach, with medium confidence; its Gene Ontology location is reachable by antibodies, with medium confidence. PROTAC: ubiquitination databases record sites on it; its protein half-life has been measured.
Gene: Protein-coding gene on chromosome 11 (1,850,904 to 1,892,267, forward strand). Ensembl gene ENSG00000130592.
Subcellular location: Cell membrane
Gene Ontology:
Molecular function: protein binding; actin binding; cytoskeletal protein binding
Biological process: cellular defense response; signal transduction
Cellular component: extracellular exosome; membrane; actin cytoskeleton; plasma membrane
Genetic constraint (gnomAD): Loss-of-function variants: 30 observed, 39.19 expected, observed/expected ratio (o/e) 0.77, 90% interval 0.57 to 1.04. The upper end of that interval is the gene's LOEUF score, 1.04, which puts it in group 4 of 6, group 1 being the genes least tolerant of losing a copy. Missense variants: 405 observed, 403.63 expected, observed/expected ratio (o/e) 1, 90% interval 0.92 to 1.09. Synonymous variants: 172 observed, 165.01 expected, observed/expected ratio (o/e) 1.04, 90% interval 0.92 to 1.18.
Homologues: Orthologues: chimpanzee LSP1 (97% identical), macaque LSP1 (88% identical), dog LSP1 (74% identical), pig LSP1 (72% identical), mouse Lsp1 (67% identical), rat Lsp1 (64% identical), tropical clawed frog lsp1 (42% identical), zebrafish lsp1a (34% identical), zebrafish lsp1b (28% identical). Paralogues in human: CALD1 (27% identical).
Diseases named in the same sentence as LSP1 in open-access papers:
LSP1 is named in the same sentence as 67 diseases in open-access papers, as found by Europe PMC text mining. Sharing a sentence is not in itself a finding about the gene and the disease. The quoted sentences say what the papers report.
breast carcinoma (45 papers, 2007 to 2024). "A positive association between the genetically predicted levels of the LSP1 protein and breast cancer risk was observed (p value of 3.63 × 10–5), while DNAJA3 showed an inverse association with breast cancer risk, with a p value of 9.15 × 10–5." (PMID 39468330, 2024). "After adjusting for GWAS-identified breast cancer risk variants, the association for protein LSP1 was still significant (adjusted p value of 6.43 × 10–3 for luminal B subtype)." (PMID 39468330, 2024). "For ER-positive, we also observed that protein LSP1 was significantly positively associated with breast cancer risk, with a p value of 2.79 × 10–5." (PMID 39468330, 2024). "This confirmed the consistent association between LSP1 protein and breast cancer risk in the current study." (PMID 39468330, 2024). "Previous studies indicated that LSP1 expression was associated with malignant biologic process in malignancies like breast cancer and Hodgkin’s disease." (PMID 32003759, 2020). "Nonetheless, our meta-analysis provides a more comprehensive assessment of the association between the LSP1 rs3817198 T > C polymorphism and breast cancer risk, and is based on a relatively large sample size." (PMID 27590509, 2016). "We found that an increased risk of breast cancer was observed for the LSP1 rs3817198 T > C polymorphism under both a homozygous model and a comparison of allele frequencies model." (PMID 27590509, 2016). "We also first found an increased risk of breast cancer with the LSP1 rs3817198 T > C polymorphism in an Asian population, although there was a stronger association in the Caucasian population." (PMID 27590509, 2016). "In the current meta-analysis, a total of 50,525 cases and 54,302 controls were retrieved to assess the association between the LSP1 rs3817198 T > C polymorphism and breast cancer risk." (PMID 27590509, 2016). "Consistent with the previous meta-analysis, we observed an increased risk of breast cancer associated with the LSP1 rs3817198 T > C polymorphism under both a homozygous model and a comparison of allele frequencies model." (PMID 27590509, 2016). "The association between the LSP1 rs3817198 T > C polymorphism and breast cancer risk has been widely investigated, but remains controversial." (PMID 27590509, 2016). "The previous meta-analysis included only 7 studies with 33,920 cases and 35,671 controls and found a significant association between the LSP1 rs3817198 T > C polymorphism and breast cancer under homozygous model and comparison of allele frequencies model." (PMID 27590509, 2016). "Previously, only one meta-analysis (in 2011) investigated the association between the LSP1 rs3817198 T > C polymorphism and breast cancer risk." (PMID 27590509, 2016). "The LSP1 rs3817198 T > C polymorphism has been widely studied for its potential association with the risk of breast cancer; however, the findings were inconclusive." (PMID 27590509, 2016). "Several publications have reported a significant association of the LSP1 rs3817198 T > C polymorphism with the risk of breast cancer." (PMID 27590509, 2016). "Pooled risk estimates indicated a significant association between the LSP1 rs3817198 T > C polymorphism and breast cancer risk." (PMID 27590509, 2016). "Our results indicate that the LSP1 rs3817198 T > C polymorphism increases susceptibility to breast cancer, especially in Caucasian and Asian populations." (PMID 27590509, 2016). "One of the other three nominally positive associations for overall NHL was found with a breast cancer SNP in the coding region for a lymphocyte-specific protein (rs3817198 in LSP1)." (PMID 24598796, 2014). "We found that the breast cancer risk allele “C” of LSP1 rs3817198 was associated with an increased risk of lung cancer." (PMID 24681604, 2014). "Our findings demonstrate a novel pleiotropic association between the breast cancer LSP1 risk region marked by variant rs3817198 and lung cancer risk." (PMID 24681604, 2014).
breast carcinoma (continued). "Our finding of pleiotropy between the breast cancer risk locus at LSP1 and lung cancer risk points toward shared etiologic mechanisms for these two cancer sites." (PMID 24681604, 2014). "Studies from genomewide association studies (GWASs) in breast cancer reveal SNPs in five genes (TNRC9, FGFR2, MAP3K1, H19, and LSP1) are associated with breast cancer susceptibility in European population." (PMID 22778704, 2012). "Variation in the LSP1 geneis associated with leukemia and lymphomas in tumor cells of Hodgkin's disease and breast cancer.Despite extensive study on the human LSP1, a comprehensive analysis on the Single Nucleotide Polymorphism (SNPs)of the gene is not available." (PMID 31787810, 2019). "Interestingly, three genes in our list (ZNF365, SGSM3, and LSP1) were significantly annotated (using Webgestalt and Disgenet) with the “category mammographic density”, that is a strong risk factor for breast cancer." (PMID 28569218, 2017). "Stratification analysis in the previous meta-analysis also indicated that the LSP1 rs3817198 T > C polymorphism was significantly associated with breast cancer in Caucasians under homozygous and recessive models and in mixed ethnicities under a homozygous model." (PMID 27590509, 2016). "Our results suggest that the LSP1 rs3817198 T > C polymorphism is a risk factor for breast cancer." (PMID 27590509, 2016). "Many polymorphisms in the LSP1 gene have been identified, and one of the most common polymorphisms, the LSP1 s3817198 T > C, has been widely studied for its potential association with breast cancer risk." (PMID 27590509, 2016). "Therefore, we performed an updated meta-analysis to provide a more comprehensive and accurate assessment of the association between the LSP1 rs3817198 T > C polymorphism and breast cancer risk." (PMID 27590509, 2016). "Also of interest is that LSP1-rs3817198 has been associated with mammographic density, consistent with the direction of the breast cancer association." (PMID 23544014, 2013). "LSP1 is reported as a susceptibility locus of breast cancer in genome-wide association studies." (PMID 22586447, 2012). "Polymorphisms in the LSP1 gene may lead to alterations in the expression and function of the protein as well as the regulation of downstream signaling pathways, thereby modulating breast cancer susceptibility." (PMID 27590509, 2016). "Additionally, in the stratified analysis by source of controls, it was noted that the LSP1 rs3817198 variant allele (C) was significantly associated with an increased breast cancer risk in population-based studies (comparison of allele frequencies model: OR = 1.09, 95% CI = 1.03–1.15, P = 0.001)." (PMID 27590509, 2016). "Interestingly, even though LSP1 is mainly expressed by lymphocytes, neutrophils, and macrophages several genome wide association studies (GWAS) have linked at least two polymorphisms (rs3817198 and rs909116) within the LSP1 gene with breast cancer risk." (PMID 23118876, 2012). "Analyses stratified by breast cancer subtypes found that SMARCC1, LSP1, and NCKAP1L are associated with luminal A and LSP1 with luminal B and ER-positive subtype." (PMID 39468330, 2024). "The corresponding genes for the remaining two proteins, LSP1 and DNAJA3, were located in previously GWAS-identified breast cancer risk loci." (PMID 39468330, 2024). "For the remaining two proteins, LSP1 and DNAJA3, the corresponding genes were in previously GWAS-identified breast cancer risk loci." (PMID 39468330, 2024). "Stratification analyses by breast cancer subtypes identified three proteins, SMARCC1, LSP1, and NCKAP1L, associated with luminal A, luminal B, and ER-positive breast cancer." (PMID 39468330, 2024). "In this first breast-tissue-based PWAS of breast cancer risk, we found that five proteins (COPG1, DCTN3, LSP1, DDX6, and DNAJA3) were significantly associated with overall breast cancer risk." (PMID 39468330, 2024).
breast carcinoma (continued). "The mutation frequency of ERCC8 (0.3%) in breast tumors was also similar to some of the other known breast cancer susceptibility genes such as STK11 (0.3%) and LSP1 (0.3%)." (PMID 33277540, 2020). "For example, a 2014 study showed association between breast cancer risk and seven breast cancer susceptibility loci (FGFR2, TOX3, STXBP4, SLC4A7, LSP1, 2q35, and 5p12)." (PMID 30249004, 2018). "For example, LSP1 is thought to play a role in mediating neutrophil activation and chemotaxis, and is expressed in both lymphocytes and endothelium, suggesting density may perhaps be, in part, a radiophenotype of genetic risk factors for breast cancer involving tissue vascularization." (PMID 25881232, 2015). "The ZNF365, ESR1, LSP1 and SGSM3 loci are also associated with breast cancer risk, implicating a shared genetic basis of mammographic density and breast cancer." (PMID 26275715, 2015). "Further evaluation of 18 loci associated with breast cancer susceptibility in the general population found that only the TOX3, LSP1, 2q35 and RAD51L1 loci were significantly associated with breast cancer for BRCA1 carriers." (PMID 23544013, 2013). "The current analyses suggest that 10 loci are now known to be associated with breast cancer risk for BRCA1 mutation carriers: 1q32, 10q25.3, 19p13, 6q25.1, 12p11, TOX3, 2q35, LSP1 and RAD51L1 all reported here and TERT." (PMID 23544013, 2013). "Four further genes, FGFR2, LSP1, MAP3K1, and TOX3, were associated with a mild increase in risk of breast cancer in a GWAS; however over 50% of breast cancers occur in women who do not carry these higher risk genotypes." (PMID 23738139, 2013). "Prominent examples are genome-wide association studies which led to the identification of novel breast cancer risk factors such as polymorphisms in FGFR2, CCND1, TOX3, MAP3K1, LSP1, CDKN2A, and 2B." (PMID 23226154, 2012). "Six of the previously identified SNPs showed a statistically significant association with breast cancer risk: rs2981582 (FGFR2), rs3803662 (TNRC9), rs12443621 (TNRC9), rs889312 (MAP3K1), rs3817198 (LSP1) and rs2107425 (H19)." (PMID 22867275, 2012). "Recent genome-wide association studies revealed strong evidence for more than 18 common breast cancer susceptibility alleles including FGFR2, CCND1, TNRC9, MAP3K1, and LSP1." (PMID 23226154, 2012). "Polymorphisms in or near TOX3, LSP1, HCN1, MAP3K1 and at 2q35 are less strongly associated with breast cancer risk than polymorphisms in FGFR2; the increased risks range from 4% to 20% with each risk allele." (PMID 19232126, 2009). "In a previous TWAS study, LSP1 was not identified as associated with breast cancer risk in breast tissue samples, but it was identified as negatively associated with breast cancer risk in cultured fibroblast cells." (PMID 39468330, 2024). "In cells grown in 3D, progestins regulate a group of breast cancer-associated genes that are also regulated in 2D including CDH10, PGR, CHEK2, LSP1, TERT, SDPR, but also a new set of 3D-exclusive genes, associated to the ECM including members of the integrin family, Laminins, and AKT3." (PMID 38565950, 2024). "We found significant upregulation of ERCC6 (p = 7.95 × 10–6) and ERCC8 (p = 4.67 × 10–6) in breast cancer and similar frequencies of ERCC6 (1.8%) and ERCC8 (0.3%) mutations in breast tumors to known breast cancer susceptibility genes such as BLM (1.9%) and LSP1 (0.3%)." (PMID 33277540, 2020). "Previously reported BRCA2-modifying alleles for breast cancer, including those in FGFR2, TOX3, MAP3K1, LSP1, 2q35, SLC4A7, 5p12, 1p11.2, ZNF365, and 19p13.1 (ER-negative only), are also associated with breast cancer risk in the general population and/or BRCA1 mutation carriers." (PMID 23544012, 2013). "Since the current literature suggested an association of HER2+ breast cancer with HSF1 but not with LSP1, we further analyzed the differential affinity of variant and ancestral miR-608 to the 3′UTR of HSF1." (PMID 22586447, 2012).
breast carcinoma (continued). "Furthermore, LSP1 and TOX3 mRNAs were targeted by miR196a-3p and miR196a-5p respectively, and these genes were also identified as novel breast cancer susceptibility markers." (PMID 21637771, 2011). "A breast cancer association was seen for six of the 14 tested SNPs; rs2981582 (FGFR2) 1.28 (1.12-1.47), rs3803662 (TNRC9) 1.20 (1.04-1.39), rs12443621 (TNRC9) 1.19 (1.04-1.35), rs889312 (MAP3K1) 1.18 (1.02-1.36), rs3817198 (LSP1) 1.17 (1.10-1.35) and rs2107425 (H19) 0.86 (0.75-0.99)." (PMID 22867275, 2012). "The local genetic correlation analysis in our study highlighted specific loci at which MD phenotypes and breast cancer showed evidence of shared heritability (DA: ESR1, ZNF365, LSP1, and MKL1; NDA: 8p11.23; PMD: ESR1 and ZNF365)." (PMID 35414113, 2022). "Whereas IFITM2 and TRIM34 have both been described to be induced by interferon but their role in carcinogenesis has not been studied, both LSP1 and PRKCDBP has been before associated with breast cancer." (PMID 23118876, 2012). "Genome-wide association studies (GWAS) have identified breast cancer susceptibility loci in or near genes such as FGFR2, TOX3 (formerly known as TNRC9), LSP1, HCN1/MRPS30, MAP3K1 and at 2q that had not previously been considered." (PMID 19232126, 2009).
leukemia (7 papers, 2007 to 2024). A malignant (clonal) hematologic disorder, involving hematopoietic stem cells and characterized by the presence of primitive or atypical myeloid or lymphoid cells in the bone marrow and the blood. "LSP1 mutations has been identified in various conditions, including leukaemia, lymphomas, Hodgkin’s disease, and BC." (PMID 39390525, 2024). "LSP1 was highly expressed in most leukemia cell lines (shown in the dotted box), while IL1R2, MPO, and CRIP1 were highly expressed in one or two leukemia cell lines." (PMID 37691822, 2023). "Additionally, as CRIP1 and LSP1 are expressed on leukemia and cytotoxic immune cells, functional investigation of CRIP1 and LSP1 by AML cells or immune cells from TIME in vitro and in vivo assays will consolidate the dual-targeting treatment strategy for AML." (PMID 37691822, 2023). "Lymphocyte-specific protein 1 (LPS1), a specific marker of leucocyte, is found in the wide range of lymphomas and leukemias, particularly of B cell origin." (PMID 28056051, 2017). "LSP1 and CRIP1 were elevated in exhausted CD8+ T cells, indicating that dual-targeting them may reverse the dysfunction of CD8+ T cells and inhibit leukemia growth to delay disease progression; however, further work is required to be carried out." (PMID 37691822, 2023).